CXCL14 (C-X-C motif chemokine ligand 14)
Diseases named in the same sentence as CXCL14 in open-access papers (continued):
Sharing a sentence is not in itself a finding about the gene and the disease.
cancer (continued). "For the first time, we identify the crucial role of CAF-derived CXCL14 in regulating the DDR and glucose metabolic reprogrammig of cancer cells." (PMID 40898244, 2025). "In cancer cells, CALB2-Ca2+-CXCL14 axis further promotes an inflammatory and immunosuppressive TME to facilitate PDAC metastasis." (PMID 39358777, 2024). "CXCL2/12 expression was negatively whereas CXCL14/17 expression was positively correlated with clinicopathological features of UCEC patients, including cancer stage, patients’ age, weight and menopause status." (PMID 38232115, 2024). "We have previously shown that decitabine treatment reverses CXCL14 promoter hypermethylation and upregulates CXCL14 expression in HPV+ cancer cells." (PMID 38400076, 2024). "There are a few chemokines that are positively correlated with ASPP1 in cancers, such as CCL28, CX3CL1, CXCL14, and CXCL17." (PMID 39830645, 2024). "In cancer cells, CALB2 further activated Ca2+-CXCL14 inflammatory axis to facilitate PDAC metastatic outgrowth and immunosuppression." (PMID 39358777, 2024). "We constructed a multi-cancer fibroblast atlas, in which fibroblasts were classified into six clusters: BAMBI+ FBs, CLDN1+ FBs, COL11A1+ FBs, CXCL14+ FBs, DPT+ FBs and RGS5+ FBs." (PMID 36744260, 2023). "Therefore, it may be worthwhile to target CXCL14/ACRK2-induced cancer metastasis in NSCLC." (PMID 37056937, 2023). "CXCL14-suppressed TNBC progression in a T cell-dependent, emphasizing CXCL14-induced alteration of Treg and CD8+ T cells on its cancer inhibitory functions." (PMID 36012586, 2022). "The dominant populations of cancer-related myofibroblasts and fibroblasts include RGS5-expressing myofibroblasts and CXCL14-expressing fibroblasts." (PMID 36463319, 2022). "Recent evidence verified that CXCL14 binds to CXCR4 and shows a synergistic effect with CXCL12 in cancers." (PMID 35452413, 2022). "Chemokine (C-X-C motif) ligand 14 (CXCL14) plays a critical role in maintaining homeostasis and inflammation in the local cell environment and regulating cancer progression." (PMID 35669852, 2022). "Cancer myoepithelial cells and myofibroblasts that surrounded DCIS exhibited an altered genetic profile characterized by high expression levels of CXCL14 and CXCL12 chemokines respectively as compared to normal intact MECs." (PMID 36510219, 2022). "For validation, we examined the expression of CCL17, CXCL14, and CXCR3 in cancer and adjacent tissues of six patients with SLC7A11 overexpression by ELISA." (PMID 35517862, 2022). "Taken together, these results imply that downregulation of CXCL14 by HPV E7-induced DNA methylation to evade host immunity contributes to suppression of host antitumor immune responses during HPV persistence and cancer progression." (PMID 29438328, 2018). "These experimental evidences from cancer research could facilitate to build a research base for endeavours in infection and inflammation or immunological research to decipher the potential mechanisms by which expression and stability of CXCL14 could be modulated." (PMID 26733763, 2016). "Taken together, these results suggest that the HPV oncoprotein E7 is sufficient to suppress CXCL14 expression; however, long-term exposure is required for dramatic repression as seen in the W12GPXY cells and HPV-positive cancers." (PMID 27143385, 2016). "While CXCL14 does not appear to be expressed highly by cancer cells, it has been found to be upregulated in other types of cancer such as pancreatic, breast, and prostate." (PMID 38339310, 2024). "The gene expression profiles revealed that CXCL14+INHBA+ fibroblasts exhibited altered gene expression patterns but did not essentially change their functions in cancer tissues." (PMID 36463319, 2022). "The significant KEGG pathways are chemokine signaling pathway (CCL5, CCL18, CCL19, CCL21, CXCL12, CXCL14, CXCL13), ​​NF-kappa B signaling pathway (CCL19, CCL21, CXCL12), intestinal immune network for IgA production (TNFRSF17, CXCL12), pathways in cancer (IGF1, CXCL12)." (PMID 35486660, 2022).
cancer (continued). "Platelet factor 4 (PF-4) or CXCL14, also known as BRAK is a highly conserved homeostatic chemokine, responsible for immune cell recruitment, maturation, and its influence on epithelial cell motility is thought to be a key modulatory factor in cancer." (PMID 33924500, 2021). "Heatmap of differential gene expression in GGN-ADC and SADC showed that some cancer-promoting genes, such as HSPB1, CCL2, CXCL14, MDK, and MMP7, were highly expressed in SADC, indicating that the cancer cells derived from SADC had a higher malignant degree than those derived from GGN-ADC." (PMID 33083004, 2020). "There is evidence from patients with cancer that plasma CXCL14 levels are sensitive to modulation by vismodegib, yet no pharmacodynamic effect on this biomarker was observed in our study of patients with IPF." (PMID 32026407, 2019). "Another interesting chemokine ligand is CXCL14, which we observed to be hypermethylated and underexpressed in two cancer types (breast and colon), but which exhibited a distinctive anti-correlative expression pattern with EZH2/DNMT1 in most cancer types." (PMID 27899617, 2017). "Another unique characteristic of CXCL14 worth mentioning is that it has a five consecutive amino acid insertion (41VSRYR45) not seen in other CXC chemokines, which was reported to be essential for its degradation in cancer cells." (PMID 26733763, 2016). "As these Tg mice showed no obvious abnormality, we propose that CXCL14 to be a promising molecular target for cancer suppression/prevention." (PMID 25765541, 2015). "CXCL14 is a cytokine expressed at high levels in normal tissues but reduced or absent in cancer cells." (PMID 25526479, 2014). "CAFs with high CXCL14 expression can increase the expression of long non-coding RNA LINC00092, which affects glycolysis by binding to 6-phosphofructo-2-kinase/fructose-2,6-bisphosphatase 2 (PFKFB2) and promoting cancer metastasis with the support of surrounding CAFs." (PMID 40136652, 2025). "However, cancer cell CXCL14 expression was not correlated with any clinicopathological characteristics of the patients." (PMID 35769715, 2022). "Additionally, the proliferative marker Ki67 expression was elevated in the epithelial cells close to the cancer MECs that expressed high CXCL14 in comparison to non-adjacent cells suggesting paracrine effects." (PMID 36510219, 2022). "Also, the PFKFB2-induced glycolytic cancer cell phenotype seems critical for the maintenance of CXCL14 secretion from CAFs, suggesting for LINC00092 a regulatory feedback loop between cancer cells and CAFs that is important for the maintenance of the tumor microenvironment." (PMID 31191327, 2019). "Doing a differential expression between the two clusters of cancer fibroblasts, we found metastatic fibroblasts were found to express higher levels of soluble factors compared to primary fibroblasts including, CXCL12, S100A6, S100A10, SFRP2,SFRP4,IGF1, CXCL14, ANGPTL4 and IL6." (PMID 30383866, 2018). "CXCL14 expression is reduced or absent from most cancer cells." (PMID 20418949, 2010). "Moreover, upregulation of CXCL13 and CXCL14 are associated with a reduction in HLA-DRA and MHC-Class II, because of which cancer-specific antigens are not presented by dendritic cells and hence cancer cells evade immunosurveillance." (PMID 32752229, 2020). "The high expression of CXCL14 in blood in healthy humans and transgenic mice did not appear to have any negative side effects, suggesting that this molecule may be a good target for the development of cost-effective methods for cancer therapy and prevention." (PMID 31014014, 2019). "To clarify whether expression of CXCL14 affected the settlement of carcinoma cell clones in host tissues in vivo and/or proliferation of the colonized carcinoma cells, we engineered oral floor carcinoma-derived HSC-2 cells in which CXCL14 expression was inducible upon doxycycline treatment." (PMID 31014014, 2019).
infection (25 papers, 2012 to 2025). The state of being infected such as from the introduction of a foreign agent such as serum, vaccine, antigenic substance or organism. "In addition, it has been reported that CXCL14 in some mammals not only has certain bactericidal activity but can also directly enhance the antibacterial function of macrophages to prevent infection caused by a variety of microorganisms." (PMID 37835641, 2023). "CXCL14 (C-X-C motif chemokine ligand 14) is an important chemokine involved in infection and immunity and plays an important role in a variety of immune-related diseases." (PMID 37835641, 2023). "Six days after infection with shCXCL14, the mRNA expression of CXCL14 was significantly downregulated in both H9 and S6 hESCs." (PMID 32708730, 2020). "Amongst cytokines, the genes for Cxcl9, Cxcl10, Cxcl13, Il-1β, Il-6, Tnf, Tnfsf10, IFN-γ, Ccl2, Ccl4, Ccl7, Ccl17, and Mif were highly up-regulated (ranging from 2- to 405-fold, p ≤ 0.05), whereas Cxcl12 and Cxcl14 were down-regulated during in vivo infection." (PMID 30857242, 2019). "Surprisingly, CXCL14 had a similar enhancement effect on infection by R5-tropic HIV-1, which requires CCR5 as a coreceptor for entry into CD4+ target cells." (PMID 28360196, 2017). "The observed enhancement of R5 HIV-1 entry by CXCL14 was dependent on CXCR4, as infection of CXCR4-deficient GHOST cells that were engineered to coexpress CD4 and CCR5 by R5 HIV-1 was not affected by CXCL14." (PMID 28360196, 2017). "The significant down-regulation of CXCL14 was also observed in bovine mammary epithelial cells at 24 h post-infection with high concentration of S. aureus in vitro." (PMID 28083515, 2016). "Infection by Ad5-CXCL14 in HPV+ HNSCC cells showed CXCL14 expression 24 hours post infection." (PMID 38911052, 2024). "Interestingly, we found that CXCL14 mRNA expression was significantly downregulated at the beginning of infection, with a slight recovery at 7 dpi." (PMID 38225621, 2024). "Interestingly, like ELR+ CXCLs, CXCL14, another neutrophil-recruiting chemokine, also displayed a down-regulated expression after infection." (PMID 31725732, 2019). "We present evidence for a role of Cxcl14 under TB-infection conditions which was previously unknown until now and provide necessary evidence for further exploration into its activity during TB infection." (PMID 27055235, 2016). "Since this chemokine seems to have a homeostatic role due its wide expression in different tissues and its down-modulation under inflammatory conditions, CXCL14/BRAK could be a key regulator in antimicrobial immunity in early phases to infection." (PMID 26062132, 2015). "For example, a cytokine receptor (CSF3R) and three chemokines (CXCL8, CXCL14, CCL20) responsible for leukocyte trafficking were upregulated during infection only in birds from less-tolerant populations." (PMID 37294834, 2023). "Regulation of chemokine transcription was also appreciated in the liver from day 2 post-infection, with an increase of CK10, CK12 and CXCL11-L1, and a decrease of CK9 and CXCL14." (PMID 25338079, 2014). "An important number of chemokines were strongly up- or down-regulated as a consequence of the infection, including up-regulation of CK3, CK10, CK12 and CXCL11_L1, and down-regulation of CK9 and CXCL14." (PMID 25338079, 2014). "The quantification of DC recruiters IP-10 (CXCL10), MIP-3α (CCL20) and BRAK (CXCL-14) by ELISA or qPCR in P2Y2+/+ and P2Y2−/− BALFs confirmed lower expression of BRAK at day 10 post-infection in the P2Y2−/− BALFs compared to P2Y2+/+ BALFs." (PMID 23185614, 2012). "Although the timing of the infection could influence the appearance of monocytes in MLN, this calls into question the role of CXCL14 in attracting “inflammatory” monocytes into LN." (PMID 24134635, 2013).
infection (continued). "Notably, the abundance of seven chemokines, such as C–C motif chemokine ligand 14 (CCL14), CCL20, CCL25, CCL5, C–X–C motif chemokine ligand 10 (CXCL10), CXCL14, and atypical chemokine receptor 3 (ACKR3), was significantly higher by infection in the R line of the TSF flock." (PMID 30678719, 2019).
adenocarcinoma (5 papers, 2012 to 2023). A common cancer characterized by the presence of malignant glandular cells. "Plasma CXCL14 levels were especially lower in adenocarcinoma than in SCLC (P=0.009) and other malignant types (P=0.001)." (PMID 35769715, 2022). "However, increased expression of CXCL14 has also been reported in adenocarcinomas." (PMID 31014014, 2019).
colon polyps (2 papers, 2022 to 2023). "The colon polyps demonstrated decreased expressions in CCL5, CCL18, CCL19, CCL21, CXCL12, CXCL14 and CXCL13 genes in this research." (PMID 35486660, 2022).
cardiovascular diseases (1 paper, 2012). "We found that four of the predicted disease genes, namely, ATF4, MBNL1, NCKAP1 and CXCL14, have been reported to be related to cardiovascular diseases." (PMID 22923290, 2012).
heart disease (1 paper, 2023). "•Low circulating CXCL14 levels were associated with worse outcomes in patients with symptomatic heart disease." (PMID 37255851, 2023). "To conclude, we provide evidence on the differential regulation of platelet-associated and circulating CXCL14 levels and their association with myocardial function in patients with heart disease." (PMID 37255851, 2023). "We characterized the surface association of CXCL14 on circulating platelets and ascertained plasma levels of circulating CXCL14 in patients with symptomatic heart disease." (PMID 37255851, 2023). "Therefore, we sought to investigate platelet-associated and circulating CXCL14 levels in patients with heart disease in this translational study." (PMID 37255851, 2023). "It is noteworthy that cellular sources other than platelets may contribute to plasma CXCL14, particularly in patients with heart disease predisposed to a chronic inflammatory state." (PMID 37255851, 2023). "•We investigated both platelet and circulating CXCL14 in 450 patients with heart disease." (PMID 37255851, 2023).
vasculopathy (1 paper, 2021). "Of note, the various CXC chemokines, such as CXCL4 (ELR-), CXCL5 (ELR+), CXCL6 (ELR+), CXCL12 (ELR−), CXCL13 (ELR−), and CXCL14 (ELR−), are thought to be associated with the development of SSc vasculopathy." (PMID 34774095, 2021).
CXCL14 also shares sentences with these, for which no sentence is quoted: lung adenocarcinoma (4 papers); chronic obstructive pulmonary disease (3); type 2 diabetes (3); Chronic colitis (2); E. coli infection (2); endometrioid carcinoma (2); idiopathic pulmonary fibrosis (2); AIDS dementia (1); amyotrophic lateral sclerosis (1); and-neck carcinoma (1); bacterial infection (1); benign tumors (1); brain tumors (1); central nervous system disorder (1); colitis (1); colon adenocarcinoma (1); Crohn disease (1); dyslipidaemia (1); eczema (1); endometrial tumor (1); endothelial dysfunction (1); enterocolitis (1); epidermodysplasia verruciformis (1); esophageal cancer (1); fibrosis (1); gestational diabetes (1); hepatitis B (1); hypercholesterolaemia (1); Hyperglycemia (1); Hyperinsulinemia (1).
A further 30 diseases each share a sentence with CXCL14 in 1 paper.